RNU7-116P (RNA, U7 small nuclear 116 pseudogene)
Gene: Small nuclear RNA gene on chromosome 14 (63,736,444 to 63,736,505, forward strand). Ensembl gene ENSG00000252749.
Homologues: Orthologues: chimpanzee U7 (98% identical). Paralogues in human: RNU7-7P (81% identical), RNU7-11P (79% identical), RNU7-143P (79% identical), RNU7-14P (79% identical), RNU7-28P (79% identical), RNU7-40P (77% identical), RNU7-10P (76% identical), RNU7-124P (76% identical), RNU7-19P (76% identical), RNU7-23P (76% identical), RNU7-25P (76% identical), RNU7-2P (76% identical), and 142 more.